TMC5 (transmembrane channel like 5)
Description:
Probable component of an ion channel (Probable). Molecular function hasn't been characterized yet (Probable).
Synonyms: FLJ13593
Tractability: Antibody: UniProt predicts a signal peptide or a membrane-spanning region; its Gene Ontology location is reachable by antibodies, with medium confidence; the Human Protein Atlas places it where antibodies can reach. PROTAC: ubiquitination databases record sites on it.
Gene: Protein-coding gene on chromosome 16 (19,410,428 to 19,499,113, forward strand). Ensembl gene ENSG00000103534.
Subcellular location: Membrane
Subcellular location (Human Protein Atlas): Plasma membrane; Nucleoplasm
Gene Ontology:
Molecular function: mechanosensitive monoatomic ion channel activity
Biological process: monoatomic ion transmembrane transport
Cellular component: extracellular exosome; plasma membrane; membrane
Genetic constraint (gnomAD): Loss-of-function variants: 76 observed, 99.18 expected, observed/expected ratio (o/e) 0.77, 90% interval 0.64 to 0.93. The upper end of that interval is the gene's LOEUF score, 0.93, which puts it in group 3 of 6, group 1 being the genes least tolerant of losing a copy. Missense variants: 1,083 observed, 1,208.8 expected, observed/expected ratio (o/e) 0.9, 90% interval 0.85 to 0.94. Synonymous variants: 430 observed, 435.95 expected, observed/expected ratio (o/e) 0.99, 90% interval 0.91 to 1.07.
Homologues: Orthologues: chimpanzee TMC5 (98% identical), macaque TMC5 (94% identical), pig TMC5 (77% identical), rabbit TMC5 (74% identical), mouse Tmc5 (73% identical), rat Tmc5 (73% identical), guinea pig TMC5 (52% identical), tropical clawed frog tmc5 (39% identical), zebrafish tmc5 (28% identical), Caenorhabditis elegans tmc-2 (16% identical), Caenorhabditis elegans tmc-1 (16% identical). Paralogues in human: TMC6 (25% identical), TMC7 (17% identical), TMC4 (16% identical), TMC8 (15% identical), TMC3 (15% identical), TMC2 (15% identical), TMC1 (14% identical).
Diseases named in the same sentence as TMC5 in open-access papers:
TMC5 is named in the same sentence as 19 diseases in open-access papers, as found by Europe PMC text mining. Sharing a sentence is not in itself a finding about the gene and the disease. The quoted sentences say what the papers report.
breast carcinoma (4 papers, 2010 to 2025). "For example, six cohorts validated that lower expression of TMC5 was associated with a higher risk of post-treatment relapse of breast cancer." (PMID 34899684, 2021). "Results showed that TMC5 was significantly associated with tumor mutation burdens in esophagus carcinoma, lung adenocarcinoma, and breast cancer." (PMID 34899684, 2021). "TMC5 is a transmembrane channel that was overexpressed in PIK3CA-mutated breast cancer." (PMID 23758962, 2013). "TMCs were regulated by DNA methylation and somatic alterations, such as TMC5 amplification in breast cancer (523/1062, 49.2%)." (PMID 34899684, 2021). "In conclusion, we show that TMC5 is an independent prognostic marker for post-treatment relapse of breast cancer." (PMID 34899684, 2021). "We identified 16 common mutations, 11 differentially methylated CpGs, and 25 copy number alterations of TMC genes in cancers, such as TMC5 amplification, were frequently detected in breast cancer (523/1062, 49.2% of patients)." (PMID 34899684, 2021). "Copy number amplification upregulated the expressions of TMC5 in breast cancer." (PMID 34899684, 2021). "NRIP3, TMC5, REEP1 and NKAIN1, whose expression had not previously been described in breast cancer, were also deregulated in the PIK3CA-mutated breast tumors." (PMID 21209903, 2010).
prostate carcinoma (3 papers, 2021 to 2025). A carcinoma that arises from epithelial cells of the prostate gland. "Beyond that, it has been reported that overexpressing TMC5 boosts prostate cancer cell proliferation and cell cycle regulation." (PMID 40883807, 2025). "An example of CTCF-loop-regulated gene is TMC5, which is transcriptionally suppressed by androgen stimulation in VCaP cells and has been reported to promote prostate cancer cell proliferation." (PMID 36997534, 2023). "TMC5 promotes prostate cancer cell proliferation and TMC7 is upregulated in cases with onset of pancreatic carcinoma." (PMID 34429071, 2021). "It has been reported that the lack of TMC5 could significantly hinder prostate cancer cell proliferation and improve cell sensitivity to 5-Fluorouracil." (PMID 40883807, 2025).
intrahepatic cholangiocarcinoma (2 papers, 2017 to 2021). A carcinoma that arises from the intrahepatic bile duct epithelium in any site of the intrahepatic biliary tree. "TMC5 is upregulated in chromophobe renal cell carcinoma and intrahepatic cholangiocarcinoma." (PMID 29069744, 2017). "Meanwhile, overexpression of TMC5 was observed in intrahepatic cholangiocarcinoma (ICC) and prostate cancer (PC)." (PMID 35096973, 2021).
lung adenocarcinoma (2 papers, 2017 to 2021). A carcinoma that arises from the lung and is characterized by the presence of malignant glandular epithelial cells. "To evaluate the possibility for clinical application, we tested the expression of DNAJB1, MCU, MPRIP, PSAP, RAI14, ZNF131 and TMC5 in 71 lung adenocarcinoma samples and paired adjacent normal tissue samples (>2 cm away from the tumor) from patients who underwent lobectomy or pneumonectomy." (PMID 29285248, 2017).
melanoma (2 papers, 2021 to 2024). A malignant, usually aggressive tumor composed of atypical, neoplastic melanocytes. "The more interesting ones, confirmed by the bibliography on melanoma, are as follows: USP15, TIPIN, TMC5, TYMP, USP19, USP8, and TFAP2B." (PMID 38928466, 2024).
colorectal cancer (1 paper, 2025). A primary or metastatic malignant neoplasm that affects the colon or rectum. "Notably, proteomic and phosphoproteomic analysis identified TMC5 as a distinctly dysregulated differential protein in colorectal cancer." (PMID 40883807, 2025). "Of interest, a recent report suggested that TMC5 was obviously dysregulated differential proteins in colorectal cancer but its role and mechanism in COAD are still unknown." (PMID 40883807, 2025).
infections in the skin (1 paper, 2016). "More interesting, we found five genes (CDKN2A, COL8A2, RASSF6, TMC4, and TMC5) from our 145 genes are associated with Walt’s disease (corrected P-value = 0.0040), which are infections in the skin caused by the human papillomavirus (HPV)." (PMID 27830726, 2016).
pancreatic adenocarcinoma (1 paper, 2025). "The upregulation of TMC5 in cancerous epithelial cells was identified in pancreatic adenocarcinoma." (PMID 40883807, 2025).
tumor (5 papers, 2010 to 2025). "TMC5 is also correlated with tumor microenvironments in HCC and associated with prognosis in HCC and lung adenocarcinoma (LUAD)." (PMID 35096973, 2021). "Tumor size and weight dropped in the presence of TMC5 deficiency, indicating that the downregulation of TMC5 could efficiently hinder the cell growth of COAD in vivo." (PMID 40883807, 2025). "Furthermore, the altered status of TMC5, containing methylation and mutation, is also correlated with tumor prognosis." (PMID 40883807, 2025). "Moreover, for patients with more advanced tumor stages (II-IV), the expression of TMC5 was also closely associated with OS." (PMID 35096973, 2021). "Beyond that, IHC staining exhibited that the positive expression rate of TMC5 was also improved in COAD tumor tissues." (PMID 40883807, 2025). "Meanwhile, low expression of TMC5 in tumor was observed in HNSC, KIRC, LUSC, and THCA (*p < 0.05, **p < 0.01, ***p < 0.001)." (PMID 35096973, 2021). "For cancers including BLCA (p < 0.001), BRCA (p < 0.001), HNSC (p < 0.001), KIRC (p < 0.001), KIRP (p < 0.05), LUAD (p < 0.001), LUSC (p < 0.001), PAAD (p < 0.001), PRAD (p < 0.001), and UCEC (p < 0.001), TMC5 was significantly differentially methylated between tumor and normal tissues." (PMID 35096973, 2021). "According to our study, TMC5 expressed differentially in human tumor tissue and normal tissue." (PMID 35096973, 2021). "Considering that glycolysis is the primary pathway for tumor cells to obtain energy, and that increased glucose uptake and lactate production are important characteristics of glycolysis activation, we examined the effects of TMC5 downregulation on glucose uptake and lactate production." (PMID 40883807, 2025). "Furthermore, to validate the functional effect of TMC5 on COAD cell malignancy in vivo, a xenograft tumor mouse model was established." (PMID 40883807, 2025). "NRIP3, TMC5 and REEP1 are differentially expressed in various other tumor types." (PMID 21209903, 2010). "Moreover, TMC5 silencing could inhibit COAD cell proliferation, migration, invasion, EMT, glycolysis, and induce apoptosis and ferroptosis in vitro, as well as repress tumor growth in vivo." (PMID 40883807, 2025).
cancer (4 papers, 2017 to 2025). A tumor composed of atypical neoplastic, often pleomorphic cells that invade other tissues. "As a member of the TMC family, TMC5 expression level was strongly linked to shorter overall survival or more advanced stages in most cancers." (PMID 40883807, 2025). "While highly expressed TMC5 is associated with better RFS/OS in some cancer types, the opposite relevance existed in others." (PMID 35096973, 2021). "We performed integrated bioinformatics analysis to provide a thorough and detailed insight of associations between TMC5 and tumorigenesis, cancer progression, and prognosis." (PMID 35096973, 2021). "Moreover, the alteration status of TMC5 including mutation and methylation was also related to cancer prognosis." (PMID 35096973, 2021). "Furthermore, the mutational data of TMC5 and its correlation with cancer prognosis were assessed." (PMID 35096973, 2021). "Additionally, the mutational status of TMC5 is also associated with prognosis in cancer patients." (PMID 35096973, 2021). "Transmembrane Channel-like 5 (TMC5) has been reported to play an oncological role in various cancers." (PMID 40883807, 2025). "First, we investigated the expression level of TMC5 in 33 human cancers in TCGA cohort with the corresponding normal tissue as control." (PMID 35096973, 2021). "The results showed that TMC4 and TMC5 have a similar expression pattern in different cancers, as do TMC6 and TMC7." (PMID 34899684, 2021). "Consistent with roles in other cancers, TMC5 silencing could dampen COAD cell proliferation, metastasis, and glycolysis." (PMID 40883807, 2025). "Notably, a comprehensive bioinformatics analysis has indicated that TMC5 expression was significantly increased in most cancer types and functions as a potential marker for cancer survival." (PMID 40883807, 2025). "Moreover, the expression of TMC5 was not only prognostic for overall survival (OS) or recurrence free survival (RFS) in various types of cancers but also correlated to OS in patients with more advanced cancers." (PMID 35096973, 2021). "TMC5 is a potential prognostic and immune marker for human cancers." (PMID 35096973, 2021). "Due to the complicated and contradictory effects of the TMEM family, TMC5 might also function intricately in human cancers." (PMID 35096973, 2021). "As a member of the TMC family, TMC5 was also detected to be related to human cancers." (PMID 35096973, 2021). "Moreover, the effects of various agents targeting other spots or pathways also correlated to TMC5 expression, which stated the function and connection of TMC5 in human cancers might be more complicated and worth further mining." (PMID 35096973, 2021). "First of all, to investigate the function of TMC5 on the genesis of human cancers, TIMER database was utilized to analyze the mRNA levels of TMC5 in 61 types of cancers." (PMID 40883807, 2025). "Different from the classification based on amino acid sequence homology, TMC5, and TMC6 belong to the same subfamily (subfamily 2), but they showed opposite relationships with immune cells in cancers." (PMID 34899684, 2021). "Further, TMC4, TMC5, TMC6, TMC7, and TMC8 were tissue-specifically and cancer-specifically expressed." (PMID 34899684, 2021). "Next, we analyzed the prognostic value of the expression level of TMC5 for OS and RFS in different cancers." (PMID 35096973, 2021). "However, whether the oncologic role of TMC5 was limited to certain cancers or broadly applicable is still not clear; therefore, we carried out a bioinformatics analysis to offer a comprehensive view." (PMID 35096973, 2021).
TMC5 also shares sentences with these, for which no sentence is quoted: breast tumors (1 paper); chromophobe renal cell carcinoma (1); COVID-19 (1); esophagus carcinoma (1); head and neck squamous cell carcinoma (1); liver fibrosis (1); lung carcinoma (1); pancreatic carcinoma (1); skin melanoma (1).